FLCN (folliculin)
Diseases named in the same sentence as FLCN in open-access papers (continued):
Sharing a sentence is not in itself a finding about the gene and the disease.
pneumothorax (continued). "Birt-Hogg-Dubé (BHD) syndrome is a rare autosomal dominant genetic disorder caused by mutations in the Folliculin (FLCN) gene and characterized by cutaneous fibrofolliculomas, multiple pulmonary cysts, spontaneous pneumothorax, and renal tumours." (PMID 41376734, 2025). "In another study, FLCN genetic testing was conducted on 7 patients with SP who also had a family history of pneumothorax." (PMID 39934870, 2025). "Further investigation is warranted to explore the development of pneumothorax from the perspective of tissue repair response in a state of FLCN haploinsufficiency." (PMID 34031471, 2021). "FLCN germline mutations cause the Birt-Hogg-Dubé (BHD) syndrome characterized by benign hair follicle hamartomas, spontaneous pneumothorax, lung cysts, and an increased risk for renal carcinoma." (PMID 32534597, 2020). "Germline inactivating mutations in the FLCN TSG can cause both BHD syndrome and non-syndromic familial pneumothorax." (PMID 29680948, 2018). "Familial clustering of recurrent pneumothorax is common in both conditions (and defines FSP), and several radiographic surveys of asymptomatic related family members carrying folliculin mutations have confirmed a high frequency of lung cysts." (PMID 19116017, 2008). "We genotyped 7 previously reported folliculin mutations, of which 2 have been observed only in FSP patients, 4 have been observed only in patients with BHD-associated pneumothorax or BHD-associated lung cysts, and 1 has been reported in both conditions." (PMID 19116017, 2008). "Haploinsufficiency of FLCN is typically associated with Birt–Hogg–Dubé syndrome (BHD, OMIM #135150), a monogenic disorder caused by point mutations in FLCN leading to lung cysts, spontaneous pneumothorax, and kidney and skin tumors." (PMID 40724914, 2025). "The syndrome occurs due to pathogenic variants in the folliculin gene (FLCN), and it is related to the development of multiple pulmonary cysts with increased risk of spontaneous pneumothorax, distinctive skin lesions called fibrofolliculomas, and renal cell carcinoma (RCC)." (PMID 41440946, 2025). "Furthermore, studies utilizing FLCN mutation testing, a genetic marker for BHD syndrome, reported more consistent and slightly higher prevalence rates of pneumothorax compared to those employing other diagnostic criteria." (PMID 40336059, 2025). "We present a unique case of BHDS in which diagnosis was made based on a combination of a left hydropneumothorax, a history of bilateral pneumothorax, absence of fibrofolliculoma skin lesions, and genetic testing showing a mutation in the FLCN gene." (PMID 37273290, 2023). "Constitutional loss-of-function variants of the tumor suppressor FLCN gene are responsible for the Birt–Hogg–Dubé (BHD) syndrome, an autosomal dominant disorder characterized by hair follicle hamartomas, kidney tumors, and spontaneous pneumothorax." (PMID 38249578, 2023). "Folliculin, encoded by FLCN gene, plays a role in the mTORC1 autophagy cascade and its alterations are responsible for the Birt–Hogg–Dubé (BHD) syndrome, characterized by follicle hamartomas, kidney tumors and pneumothorax." (PMID 38249578, 2023). "The recurrence of PSP was taken as a dependant variable for ‘age of onset of first spontaneous pneumothorax’, while patient gender, presence/absence of family history, tobacco habits and presence of FLCN pathogenic mutations were considered as co-factors." (PMID 35477461, 2022). "Therefore, the most common presentation pneumothorax in setting of characteristic cystic lung lesions or a family history of pneumothorax should suggest the need for FLCN gene testing to make timely diagnosis." (PMID 34001170, 2021). "We therefore hypothesized that impaired functions in BHDS-PMCs due to long-lasting FLCN haploinsufficiency would contribute to the development of pneumothorax." (PMID 34031471, 2021).
pneumothorax (continued). "According to these reports, other constituent cells of the lungs are also likely to be affected by the FLCN haploinsufficiency and consequently, lung cysts may develop and result in the development of pneumothorax." (PMID 34031471, 2021). "The exact mechanism of FLCN mutations leading to pulmonary cysts and pneumothorax in BHDS patients has not yet been fully elucidated." (PMID 33240319, 2020). "FLCN mutation screening is recommended for patients with RCC and pulmonary cysts without cutaneous lesions, especially for those with a clear family history of RCC or pulmonary cysts/pneumothorax." (PMID 28069055, 2017). "Two non-related patients with (recurrent) pneumothorax starting at age 14 accompanied by multiple basal lung cysts on thoracic CT underwent FLCN germline mutation analysis." (PMID 24994497, 2014). "Again, ascertainment has varied for cohorts of patients and the lifetime risk of pneumothorax for FLCN mutation carriers has not yet been established." (PMID 22146830, 2011). "FLCN mutations have been identified in sporadic renal tumors, while mutations of FLCN have been detected in patients with sporadic and familial spontaneous pneumothorax without other phenotypic features of BHDS." (PMID 20403193, 2010). "Studies using FLCN mutation testing may thus capture a more homogeneous population with a higher likelihood of having BHD syndrome, leading to more consistent and slightly higher prevalence rates of pneumothorax." (PMID 40336059, 2025). "In the setting of cystic lung disease, recurrent spontaneous pneumothorax in a non-smoker should alert the pathologist to the underlying lung pathology, which may be linked to FLCN gene mutation, in order to find further evidence of BHD." (PMID 39300538, 2024). "In addition to individuals diagnosed with BHDS, pathogenic FLCN variants have also been described in individuals with familial pneumothorax but no other features of BHDS." (PMID 34267338, 2021). "No clear correlations between FLCN variants and specific phenotypes have been established, though some studies suggest different mutations may carry distinct risk profiles for cancer, lung cysts, and pneumothorax." (PMID 41193855, 2026). "The possibility of FLCN haploinsufficiency in pleural mesothelial cells (PMCs) contributing to development of pneumothorax has not yet been clarified." (PMID 34031471, 2021). "In patients with RCC and pulmonary cysts but without cutaneous lesions, screening for mutations in the FLCN gene should be performed, especially for those with a family history of RCC or pulmonary cysts (pneumothorax)." (PMID 28069055, 2017). "The difficulty in unmasking BHD patients in apparently sporadic RCC patients is illustrated by the negative family history for pneumothorax and RCC in the two FLCN mutation carriers." (PMID 26603437, 2016). "Families of index BHDS cases and patients with a family history of recurrent spontaneous pneumothorax should be considered for screening for the FLCN gene, even in the absence of other features, in view of the potentially lethal consequences." (PMID 20403193, 2010). "The Folliculin (FLCN) gene, identified in 2002, is responsible for Birt-Hogg-Dubé (BHD) syndrome, an autosomal dominant genetic disorder characterized by fibrofolliculomas, pulmonary cysts, increased spontaneous pneumothorax frequency, and bilateral multifocal renal tumors." (PMID 40143966, 2025). "However, neither the role of pleural mesothelial cells (PMCs) in pneumothorax, nor the effect of FLCN haploinsufficiency on PMCs in patients with BHDS (BHDS-PMCs) have yet been elucidated." (PMID 34031471, 2021). "In five families without an identifiable FLCN mutation (BHD 2, 5, 9, 25 and 28) the clinical diagnosis BHD was based on histologically confirmed multiple fibrofolliculomas; in one of these kindreds both pneumothorax and renal cancer occurred (BHD 25)." (PMID 22146830, 2011).
renal tumors (46 papers, 2008 to 2026). "Inactivation of the wildtype FLCN allele by a somatic second-hit in the kidneys of patients with BHDS cause kidney tumors and the gene is therefore known as a classical tumor suppressor." (PMID 41193855, 2026). "A comprehensive review of 204 families with at least one manifestation of BHDS indicated that individuals with the FLCN variant have an estimated 19% risk of developing renal tumors in males and 21% in females." (PMID 38963008, 2024). "In this study, we examined clinical and genetic data from a patient with BHDS‐associated renal tumors in China and identified a novel variant in the FLCN gene region, which was confirmed by Sanger sequencing of her large family members." (PMID 38963008, 2024). "The dysregulation of the PGC-1a-TFAM signaling pathway is particularly notable in kidney tumors bearing FLCN mutations and in tumors originating from other organs with comparatively diminished FLCN expression levels." (PMID 39201746, 2024). "Genetic screening where renal tumour was the only clinical symptom in the index patient revealed a FLCN variant in eleven of 21 cases, emphasizing that BHDS is common in this disease." (PMID 35176117, 2022). "Glycogen accumulates in phagocytes from hematopoietic-linage-specific FLCN-deficient mice, the kidneys from kidney-specific FLCN-depleted mice, and renal tumors from BHD patients." (PMID 33981707, 2021). "Most of the initial studies addressed the contribution of FLCN loss to the development of BHD-derived renal tumors." (PMID 33981707, 2021). "Although initial studies focused on deciphering how FLCN loss results in BHD-associated renal tumors, evidence accumulated during the last decade indicate that FLCN is a pleiotropic protein implicated in multiple cellular processes." (PMID 33981707, 2021). "Birt-Hogg-Dubé (BHD) is an autosomal dominant genetic syndrome caused by germline mutations in the FLCN gene that predisposes patients to develop renal tumors." (PMID 29774133, 2018). "Here we describe an FLCN mutation in a 55-year-old patient who presented himself with progressive weight loss, bilateral kidney cysts and renal tumors." (PMID 28499369, 2017). "Germline mutations in the FLCN gene are responsible for the development of fibrofolliculomas, lung cysts and renal neoplasia in Birt-Hogg-Dube' (BHD) syndrome." (PMID 20573232, 2010). "Variants in the FLCN gene diminish the tumor suppressor effect of these signaling pathways, triggering renal tumors in renal distal tubules in accordance with the second‐hit hypothesis." (PMID 38963008, 2024). "Previous studies have reported the co‐occurrence of somatic variants in the FLCN gene in both BHDS‐associated renal tumors and parathyroid adenomas, which aligns with our findings and strongly supports this hypothesis." (PMID 38963008, 2024). "Birt‐Hogg‐Dubé (BHD) syndrome is an inherited familial cancer syndrome characterized by the development of cutaneous lesions, pulmonary cysts, renal tumors and cysts and caused by loss‐of‐function pathogenic variants in the gene encoding the tumor‐suppressor protein folliculin (FLCN)." (PMID 36987696, 2023). "Therefore, this feedback loop between TFEB and mTORC1 plays a key role in the development of FLCN-deficient renal tumors." (PMID 33981707, 2021). "Upregulation of these two Rags may explain enhanced activation of mTORC1 associated with FLCN loss in BHD-derived renal tumors." (PMID 33981707, 2021). "Although the FLCN-FNIP GAP activity toward RagC/D identifies this complex as a positive regulator of mTORC1, renal tumors from BHD patients containing FLCN germline mutations showed increased mTORC1 activity, as well as higher levels of phosphorylation of mTORC1 substrates." (PMID 32195250, 2020). "At the same time, FLCN overexpression experiments were also performed to verify whether the increasing FLCN expression levels in renal tumors caused by other factors contributed to the alleviation of tumor cell deterioration." (PMID 32850947, 2020).
renal tumors (continued). "All patients displayed FLCN germline mutations; somatic FLCN mutations were observed in 25 out of the 29 kidney tumors: 20 tumors displayed frameshift/nonsense mutations or loss of heterozygosity at the level of the allele not affected by the germline mutation." (PMID 32751108, 2020). "In addition, strains of rats, mice, and dogs with a germline mutation in the Flcn gene developed spontaneous kidney tumors with a loss of function in the second allele pointing to a tumor suppressor function of FLCN." (PMID 24763318, 2014). "The SM locus contains a gene encoding another renal kidney tumor suppressor, FLCN." (PMID 23922894, 2013). "Dr Laura Schmidt (NCI, USA) used high-throughput small molecule screens in FLCN-deficient human kidney cancer cell lines to identify several classes of compounds that were cytotoxic in vitro and subsequently tested their therapeutic efficacy in the FLCN-mutant Nihon rat renal tumor model." (PMID 35070081, 2022). "In addition, as a tumor suppressor protein, the novel mutation may decrease the levels of FLCN protein and induce the renal tumor." (PMID 28785590, 2017). "This study indicates that pathogenic FLCN variants increase the risk of CRC and malignant melanoma, alongside the established risk of kidney tumors." (PMID 41193855, 2026). "We performed a register-based matched cohort study of 353 Swedish born individuals with verified pathogenic variants in FLCN to study the association between BHDS and other cancer types than kidney tumors." (PMID 41193855, 2026). "A Chinese proband diagnosed with BHDS due to renal tumors underwent next‐generation sequencing (NGS), revealing a novel variant in the FLCN gene." (PMID 38963008, 2024). "Fourth, mutations in FLCN, which similarly disrupt the FLCN/FNIP GAP complex, result in renal tumors, which can be abrogated by the simultaneous inactivation of TFEB." (PMID 37627070, 2023). "Individuals affected with BHD inherit germline FLCN variants, whereas somatic “second hit” alterations are found in BHD‐associated kidney tumors resulting in loss of function." (PMID 36987696, 2023). "FLCN gene encodes the folliculin protein, which could act as a tumor suppressor, and its germline or somatic mutation may be associated with different kinds of cancers, such as fibrofolliculomas, lung cysts, renal tumors, or renal neoplasia in Birt–Hogg–Dubé (BHD) syndrome." (PMID 35409691, 2022). "Despite the role of FLCN as a positive modulator of mTORC1 activity, mTORC1 is hyperactivated in renal tumors from BHD patients or FLCN knockout mouse models." (PMID 33981707, 2021). "Germline mutations in the Folliculin (FLCN) tumor suppressor gene cause Birt–Hogg–Dubé (BHD) syndrome, a rare autosomal dominant disorder predisposing carriers to kidney tumors." (PMID 33459596, 2021). "Importantly, FNIP1 and FNIP2 were essential also for the tumor suppressive function of FLCN at the level of kidney tissue, thus supporting the view that the development of kidney tumors in BHD patients may be due to the loss of essential FLCN-FNIP interactions." (PMID 32751108, 2020). "Our pretest result indicated that the FLCN gene acts as a regulator of renal tumors, and its knockdown resulted in a significant increase in HIF2α protein levels." (PMID 32850947, 2020). "It is also reported that the inactivation of FLCN is an initial step in the development of renal tumors in BHD." (PMID 32850947, 2020). "To further test the efficacy of sirolimus on human FLCN-deficient RCC growth in vivo, we developed a xenograft mouse model by inoculating human FLCN-deficient RCC line, UOK 257-1, a cell line derived from a human BHD renal tumor." (PMID 26418749, 2015). "BHD patients carry a loss of function germline mutation in one FLCN allele and acquire a second hit somatic mutation or loss of heterozygosity (LOH) in the remaining wild-type copy in their renal tumors." (PMID 24763318, 2014).
renal tumors (continued). "Increased TFE3 activity is a downstream event induced by FLCN inactivation and is likely to be important for renal tumor development." (PMID 21209915, 2010). "Consistently, GREM1, the antagonist of BMP that signals through SMADs was highly up-regulated in mutant FLCN and FLCN-null UOK257 cells although its expression was low in BHD-associated renal tumors." (PMID 20573232, 2010). "Our data demonstrate a role for FLCN in the regulation of key molecules in TGF-β signaling and confirm deregulation of their expression in BHD-associated renal tumors." (PMID 20573232, 2010). "We measured protein expression of SMAD2, SMAD3, phospho-SMAD3 (pSMAD3) and FLCN in renal tumors from BHD patients (n = 11) and normal human kidney tissue (n = 5)." (PMID 20573232, 2010). "Somatic mutations or loss of heterozygosity in the remaining wild type copy of the FLCN gene have been found in renal tumors from BHD patients suggesting that FLCN is a classic tumor suppressor gene." (PMID 20573232, 2010). "Either somatic "second hit" mutations predicted to truncate the protein or loss of heterozygosity at the BHD syndrome locus was identified in 70% of renal tumors from BHD patients supporting a tumor suppressor function for FLCN." (PMID 20573232, 2010). "GPNMB expression was highly dependent on FLCN inactivation not only in cultured cells but also in the kidneys and renal tumors of the human patient and in vivo mouse models." (PMID 21209915, 2010). "Mutations in the tumor suppressor gene Folliculin (FLCN) are responsible for Birt-Hogg-Dube’ (BHD) syndrome, a rare inherited condition that predisposes affected individuals to skin tumors, pulmonary cysts, and kidney tumors." (PMID 40189703, 2025). "Mutations in a tumour-suppressor gene (FLCN gene) result in BHD syndrome, an autosomal dominant condition, which is usually characterized by the formation of pulmonary cysts, skin fibrofolliculomas, and renal tumours." (PMID 40166800, 2025). "RCC might manifest as hereditary forms, accounting for 2% of all renal neoplasia; mostly associated to germline mutations of Von Hippel–Lindau (VHL) and folliculin (FLCN) genes." (PMID 38512353, 2024). "While depletion of FLCN in certain cell lines impairs mTORC1 activation as determined by decreased phosphorylation of S6K, FLCN loss does not affect or even increases mTORC1 activity in cells or BHD-derived kidney tumors." (PMID 33981707, 2021). "Recent studies have shown that mTORC is activated in kidney tumors that lack FLCN." (PMID 32850947, 2020). "Although FLCN is considered to function as a tumor-suppressor gene, the established propensity for cancer in BHD syndrome so far is limited to the renal neoplasms; whether BHD syndrome confers the risk of developing colorectal cancer remains conjectural." (PMID 27871249, 2016). "However, most sporadic tumors lack FLCN mutations and the extent to which the BHDS-derived renal tumors share genetic defects associated with the sporadic tumors has not been well studied." (PMID 21162720, 2010). "Notably, several key genes involved in TGF-β signaling, such as TGFB2, INHBA, THBS1 and SMAD3, were down-regulated in FLCN-null and mutant FLCN cells as well as in the BHD-associated renal tumors." (PMID 20573232, 2010). "Loss‐of‐function pathogenic variants of FLCN are known to cause Birt‐Hogg‐Dubé (BHD) syndrome, an autosomal dominant disorder characterized by pulmonary and renal cysts, spontaneous pneumothorax, benign cutaneous fibrofolliculomas, and an increased risk of developing kidney tumors." (PMID 36987696, 2023). "In order to determine whether the genes that were regulated by FLCN in in vitro cell culture were differentially expressed in renal tumors from BHD patients compared to normal kidney parenchyma, we performed quantitative RT-PCR using RNA isolated from these tissues." (PMID 20573232, 2010).